GMPS (guanosine monophosphate synthase)
Description:
Catalyzes the conversion of xanthine monophosphate (XMP) to GMP in the presence of glutamine and ATP through an adenyl-XMP intermediate.
Synonyms: GATD7
Tractability: Small molecule: a drug acting on it is in phase 2 or 3 trials; a structure with a bound ligand is known; a high-quality ligand is known; it has a high-quality binding pocket. PROTAC: ubiquitination databases record sites on it; its protein half-life has been measured; a small molecule that binds it is known.
Target class: Enzyme; Ligase
Gene: Protein-coding gene on chromosome 3 (155,870,591 to 155,944,020, forward strand). Ensembl gene ENSG00000163655.
Subcellular location: Cytoplasm, cytosol
Subcellular location (Human Protein Atlas): Cytosol; Mitochondria
Pathways (Reactome):
Drug ADME: Azathioprine ADME
Metabolism: Purine ribonucleoside monophosphate biosynthesis
Gene Ontology:
Molecular function: GMP synthase (glutamine-hydrolyzing) activity; GMP synthase activity; ATP binding
Biological process: GMP biosynthetic process; purine nucleobase biosynthetic process; purine ribonucleoside monophosphate biosynthetic process; purine nucleotide biosynthetic process
Cellular component: cytosol
Genetic constraint (gnomAD): Loss-of-function variants: 4 observed, 6.83 expected, observed/expected ratio (o/e) 0.59, 90% interval 0.29 to 1.33. That is too few expected variants to judge how well the gene tolerates losing a copy. Missense variants: 90 observed, 93.62 expected, observed/expected ratio (o/e) 0.96, 90% interval 0.81 to 1.14. Synonymous variants: 30 observed, 32.6 expected, observed/expected ratio (o/e) 0.92, 90% interval 0.69 to 1.25.
Homologues: Orthologues: pig GMPS (99% identical), rabbit GMPS (99% identical), macaque GMPS (98% identical), mouse Gmps (98% identical), rat Gmps (96% identical), dog GMPS (95% identical), guinea pig GMPS (93% identical), tropical clawed frog gmps (92% identical), zebrafish gmps (86% identical), chimpanzee GMPS (74% identical), Drosophila melanogaster bur (57% identical), Caenorhabditis elegans gmps-1 (50% identical).